TERLR1 (TERT regulating lncRNA 1)
Synonyms: BC032469; CTD-3080P12.3
Gene: Long non-coding RNA gene on chromosome 5 (1,173,141 to 1,182,901, reverse strand). Ensembl gene ENSG00000249201.
Diseases named in the same sentence as TERLR1 in open-access papers:
TERLR1 is named in the same sentence as 4 diseases in open-access papers, as found by Europe PMC text mining. Sharing a sentence is not in itself a finding about the gene and the disease. The quoted sentences say what the papers report.
breast carcinoma (1 paper, 2024). "Applying these 9982 models to GWAS data using S-PrediXcan, one lncRNA gene CTD-3080P12.3 (also known as TERLR1) was associated with overall breast cancer risk at the Bonferroni-corrected significance of P < 5.0 × 10−6 (0.05/9982)." (PMID 38697998, 2024). "CTD-3080P12.3, also known as TERLR1, is located at a well-known breast cancer risk locus (lead variant rs2853669, also known as the TERT SNP), however, this gene has not been reported in association with breast cancer in any previous studies." (PMID 38697998, 2024).
TERLR1 also shares sentences with these, for which no sentence is quoted: cancer (1 paper); gastric cancer (1); tumor (1).